MIR4700 (microRNA 4700)
Synonyms: hsa-mir-4700; mir-4700
Gene: MicroRNA gene on chromosome 12 (120,723,193 to 120,723,266, forward strand). Ensembl gene ENSG00000284143.
Homologues: Orthologues: chimpanzee MIR4700 (100% identical).
Diseases named in the same sentence as MIR4700 in open-access papers:
MIR4700 is named in the same sentence as 2 diseases in open-access papers, as found by Europe PMC text mining. Sharing a sentence is not in itself a finding about the gene and the disease.
MIR4700 shares sentences with these, for which no sentence is quoted: psychiatric disorder (1 paper); schizophrenia (1).